RELA (RELA proto-oncogene, NF-kB subunit)
Diseases named in the same sentence as RELA in open-access papers (continued):
Sharing a sentence is not in itself a finding about the gene and the disease.
tauopathy (1 paper, 2022). Neurodegenerative disorders involving deposition of abnormal tau protein isoforms (tau proteins) in neurons and glial cells in the brain. "In addition, the RELA and JUN TFs link back to protein homeostasis pathways (i.e., ‘ubiquitin protein ligase binding’), which is reflected in the gradual accessibility increments of tauopathy- and degradation system-associated genes (online resource)." (PMID 35976433, 2022).
thrombotic microangiopathy (1 paper, 2021). The syndromes of microangiopathic hemolytic anemia, thrombocytopenia, and variable signs of organ impairment, due to platelet aggregation in the microcirculation. "Moreover, in pathological conditions where RelA (the p65 subunit of NF-κB) is upregulated, such as thrombotic microangiopathy— —CMIP expression in glomeruli is repressed." (PMID 33917766, 2021).
type 1 diabetes (1 paper, 2023). "Interestingly, we found that in type 1 diabetes donors with an inverse relationship between RAGE and GCG (hereby, T1D-adolescents), there was increased α cell RELA (vs. remaining type 1 diabetes donors)." (PMID 37558746, 2023). "We found that MAPK1, but not RELA, was significantly reduced in the α cells of donors with type 1 diabetes (vs. control and autoantibody-positive donors), whereas JAK1 was expressed at insignificant levels within the islets in all groups." (PMID 37558746, 2023).
type 1 interferonopathies (1 paper, 2025). "Patients with dominant negative variants in RELA have additional inflammatory presentations compared with RELA haploinsufficiency, including IBD, JIA, and skin manifestations, resembling type 1 interferonopathies." (PMID 40842819, 2025).
uterine tumors (1 paper, 2022). "In addition, the histopathological and molecular features of three uterine tumors carrying SRF::RELA fusions were recently identified and compared to SRF::RELA-positive perivascular myoid tumors arising in other anatomical districts." (PMID 36421692, 2022).
uveitis (1 paper, 2023). An inflammatory process affecting a part of or the entire uvea. "In addition, studies have shown that MAPK1, RELA, and JUN can effectively control the progression of uveitis." (PMID 37653797, 2023). "JUN, RELA, and MAPK may play important roles in the treatment of uveitis by SNS." (PMID 37653797, 2023).
tumor (315 papers, 2001 to 2026). "Taken together, these results indicate that EMT program is initiated in MT‐PHHs upon RELA loss, thereby inducing tumor metastasis." (PMID 40919676, 2025). "Clinically, low RELA expression is positively associated with poor prognosis and large tumor size in HCC patients." (PMID 40919676, 2025). "In this regard, RelA activation in lung tumor cells or tumor-associated myeloid cells/macrophages (TAMs) is associated with disease progression and poor patient survival." (PMID 38385745, 2024). "The heterodimers formed by p65 (encoded by RELA) and p50 are in charge of gene transcription when activating the canonical NF-κB signaling pathway, and the malignant phenotypes of tumor cells are closely related to activation of canonical NF-κB." (PMID 37101128, 2023). "Our previous study found that METTL3 acts as a tumor suppressor in PTC by influencing the m6A modification of c-Rel and RelA mRNAs, thereby altering tumor-associated neutrophils (TANs) infiltration to regulate tumor growth." (PMID 36522683, 2022). "Expression of RELA chimeras results in constitutive activation of NF-κB signaling pathway and associated resistance of the tumor to chemo and radiation therapies." (PMID 34638438, 2021). "For example, RELA can drive tumor-associated macrophages to suppress CD8+ cytotoxic T lymphocytes for tumor promotion, indicating a RELA-targeted immunotherapy for lung cancer." (PMID 33558586, 2021). "RELA is implicated in tumor–stroma interactions and correlates strongly with the severity of tumor infiltration by inflammatory cells in NSCLC patients." (PMID 34249899, 2021). "In subcutaneous and intrabursal xenografts of OC cell lines with inducible knockdown of RelA or RelB with shRNA, loss of either RelA or RelB significantly reduced tumor burden compared to controls." (PMID 31443240, 2019). "Comparison of tumor size, grades had high significance (p < 0.005) and revealed significant association with RelA nuclear (p < 0.005) and cytoplasmic localization (p < 0.005)." (PMID 30225173, 2018). "At this point tumours start to become visible on the liver surface in WT mice and therefore this is the optimal time to investigate if the RelA T505A mutation resulted in earlier onset of tumorigenesis." (PMID 26853469, 2016). "Modification of this site provides a mechanism to antagonise and limit aspects of RelA function associated with its tumour-promoting activities." (PMID 26853469, 2016). "As expected, administration of DHMEQ significantly suppressed the nuclear translocation of RelA/p65 both in tumor and stromal cells of HAI-1-deficient ApcMin/+ mice." (PMID 27612426, 2016). "We also examined the effect of DHMEQ on nuclear translocation of RelA/p65 in the tumor tissues of HAI-1-deficient ApcMin/+ mice." (PMID 27612426, 2016). "Intriguingly, RelA activity is associated with opposing pro- proliferative oncogenic and anti- proliferative tumor-suppressive roles." (PMID 26460486, 2015). "RELA fusion mutations can activate NF-κB abnormally, contributing to tumor formation." (PMID 39910053, 2025). "Additionally, the prognosis analysis results indicate that high RELA expression in tumour tissues is associated with poor overall survival." (PMID 40635685, 2025). "RELA, an encoder of the essential subunit of nuclear factor‐κB (NF‐κB), is involved in inflammation, immunity, tumourigenesis, and apoptosis, all of which are related to the progress and prognosis of tumour." (PMID 36408734, 2023).
tumor (continued). "As anticipated, TNFα increased SF-767 cell invasion because of other metabolic stimuli due to the presence of LDL protein and receptors, which increased the cell proliferation turnover of growing tumor cells in this study and caused NF-κB p65 (RelA) activation." (PMID 37892820, 2023). "For example, c-REL may be a suitable target for GC tumours with strong NF-κB pathway activity, RELA for plasmablast-associated tumours, and RELB and/or NF-κB2 for the subset of DLBCL cases with nuclear translocation of these subunits." (PMID 36289712, 2022). "Initial studies described that both UFL1 and the adaptor protein C53 (CDK5RAP3), reported to function as a tumor suppressor, regulates NF-kB signaling by associating directly with RELA (p65), abolishing its phosphorylation to enhance interaction with HDAC thereby stimulating NF-κb activity." (PMID 33578803, 2021). "Furthermore, the reduced tumor burden was linked to decreased Stat3 and NF-κB (RelA/p65) activation." (PMID 34680353, 2021). "Loss of RelA/p65 resulted in the induction of E-cadherin expression in both A549 and H1437 cells and in the suppression of N-cadherin and vimentin in A549 cells in both cells grown as tumour xenografts, or cultured as monolayers." (PMID 34503110, 2021). "RELA level is also associated with a lower tumor volume in our cohort." (PMID 28327132, 2017). "Notably, our findings provide direct genetic evidence that RELA acts as a tumor suppressor in human HCC progression, whose loss may functionally substitute for KRASG12D in driving HCC progression." (PMID 40919676, 2025). "Hence, in NSCLC, RelA may promote the expression of secretory genes encoding proinflammatory cytokines and chemokines responsible for attracting inflammatory cells to the tumor site, with possible pro-tumor or anti-tumor functions." (PMID 26147201, 2015). "Moreover, tumor-associated macrophages, which are refractory to LPS exhibit strong overexpression of p50 and fail to induce TNFα expression despite normal levels of p65/RelA and its ability to re-localize to the nucleus upon LPS treatment." (PMID 24843008, 2014). "In particular, RELA, a core component of the NF-κB pathway, and SP1, a pleiotropic transcription factor with oncogenic potential, are widely implicated in tumor progression, proliferation, and immune evasion." (PMID 41303462, 2025). "In HNC, overexpression of RELA has been associated with tumor progression, resistance to chemotherapy, and increased invasiveness through pathways such as IKK-NFκB/RELA and USP14-mediated signaling." (PMID 40606440, 2025). "Subsequent analysis using the TCGA database demonstrated that RelA expression was significantly upregulated in CRC tissues compared to adjacent non-tumor tissues, and its upregulation was correlated with poor prognosis." (PMID 40860198, 2025). "We next examined the correlation between RELA mRNA expression and clinicopathological parameters in clinical HCC patients and found that RELA expression was negatively associated with larger tumor size (P = 0.0177)." (PMID 40919676, 2025). "This tumor-suppressive effect involves inhibition of the NF-κB pathway, as evidenced by reduced nuclear localization of RelA and decreased expression of NF-κB target genes, including cIAP, XIAP, BCL2, and Survivin." (PMID 40562870, 2025). "Validation using our own samples further confirmed the elevated expression of RelA in CRC tumor tissues." (PMID 40860198, 2025). "Immunofluorescence analysis indicated that both ALDH1B1 expression levels and nuclear RelA levels were increased in tumor cells constrained in lung capillaries, compared to tumor cells outside capillaries." (PMID 41390768, 2025). "In NSCLC, the transmembrane mucin MUC3A—overexpressed in tumor tissues—is regulated by the NF-κB pathway through its interaction with RELA (p65)." (PMID 40655139, 2025).
tumor (continued). "Nuclear PD-L1 positively correlates with immune response-related transcription factors including STAT3, RelA (p65), and c-Jun40, interacting with these factors on DNA to influence anti-tumor immunity." (PMID 40573881, 2025). "Here, our screening identified RELA as a tumor suppressor in HCC, supported by clinical data and validated in both subcutaneous and long‐term orthotopic induced HCC (iHCC) models." (PMID 40919676, 2025). "Using this cohort, we determined the correlation between RELA and NFkB1 expression levels from 24,489 tumor cells." (PMID 41285837, 2025). "METTL3, as the writer of m6A, plays a pivotal tumour-suppressor role in PTC carcinogenesis through c-Rel and RelA inactivation of the nuclear factor κB (NF-κB) pathway to regulate tumour growth." (PMID 38993572, 2024). "To further confirm IL-1β signaling, we tested the ability of B cells to activate IL-1β-dependent NFκB signaling in tumor cells by assessing phosphorylation of serine 536 of the p65 (RELA) subunit." (PMID 39801513, 2024). "RelA overexpression also enhanced CTL cytotoxicity toward tumor cells, whereas RelA knockdown decreased it, highlighting RelA’s critical role in CTL cytotoxicity." (PMID 39292167, 2024). "Here, the authors show that tumor extracellular vesicles mediate mitochondrial DNA transfer to CECs, initiating mitochondrial activation and RelA-induced TGFβ1 expression, leading to tumor progression." (PMID 38688896, 2024). "Based on the results from this xenograft model, RelA/p65 Ser536 phosphorylation clearly inhibited tumor progression." (PMID 39498383, 2024). "The RELA gene expression level was higher in the normal tissue than in the tumor tissue in UCEC patients, whereas it was higher in the tumor than the normal tissue in COAD, STAD, and GBM patients." (PMID 38542508, 2024). "Inhibiting Ref-1 activity with APX3330 reduces RelA activity, decreasing inflammation and enhancing tumor cell sensitivity to chemotherapy." (PMID 39635662, 2024). "Ref-1 maintains RelA in an active state, promoting the transcription of genes involved in inflammation and tumor cell survival." (PMID 39635662, 2024). "Inhibition of RelA (NFκB p65) using anti-sense oligonucleotides retarded the tumor growth of PX1 xenografts, suggest the importance of NFκB in HTLV1 associated tumors." (PMID 38571491, 2024). "In papillary thyroid carcinoma (PTC), METTL3 is able to cooperate with YTHDF2 to inhibit IL-8 secretion, reduce tumor-associated neutrophil (TAN) recruitment, and inhibit tumor growth using c-Rel and RelA as downstream modification targets." (PMID 39072324, 2024). "They showed that miR-7-5p reduces tumor cell viability, migration, and invasion partly by suppressing NF-κB activity through direct targeting of the RelA subunit." (PMID 38785501, 2024). "Despite frequent upregulation of both TNFα and RELA in PDAC tumours, the dynamics and regulation of single-cell RELA translocation, as well as RELA transcriptional output, are poorly understood for PDAC cells." (PMID 39110005, 2024). "In vivo experiments demonstrated that a phosphorylation-mimetic mutant of RelA/p65 Ser536 (p65/S536D) prevents tumor progression and metastasis." (PMID 39498383, 2024). "Numerous studies highlight NF-κB p65 (RelA) and TNFα mediated exacerbation of inflammation in the tumor microenvironment." (PMID 37892820, 2023). "IHC revealed a higher number of IBA1+ invasive GBM cells at the tumor periphery, accompanied by elevated levels of TAMs in RelA-WT cells compared to RelA-MUT cells." (PMID 37461511, 2023). "Collectively, these results showed that inhibition of NF-κB signaling by RelA ablation delayed tumor onset and prolonged mouse survival, revealing a tumor-promoting role of NF-κB in SCLC." (PMID 36653597, 2023). "To evaluate the tumor forming capacity of these mutant GSCs in vivo, we orthotopically engrafted RelA-WT or RelAMUT cell lines into mice." (PMID 37461511, 2023).
tumor (continued). "It has been suggested that targeting NF-κB p65 (RelA) increases survival by promoting a tumor microenvironment (TME) that is less immunosuppressive and more receptive to immunomodulation." (PMID 37892820, 2023). "And there was a positive correlation between RELA expression and tumor grade, including pT_stage, pN_stage, and pM_stage." (PMID 37770919, 2023). "We show that inhibition of NF-κB signaling by depletion of NEMO or RelA considerably delayed tumor onset, slowed tumor growth and significantly prolonged mouse survival." (PMID 36653597, 2023). "A pharmacogenomics study pointed out that in GBM, CBD tumor suppression properties proceeded from preventing NF-κB subunit RELA phosphorylation on serine-311 and promoting RELA DNA binding." (PMID 38136172, 2023). "RELA activity has been attributed to the promotion and activation of the NF-κB which holds tumor-promoting roles." (PMID 37624039, 2023). "CIGB-552 is a synthetic anti-tumor peptide that stimulates the ubiquitination of RelA, a subunit of NF-κB, in lung cancer cells, therefore decreasing the anti-apoptotic action of NF-κB and promoting the death of tumor cells." (PMID 36776284, 2023). "Our experimental validation of miR-335-5p noted its increased expression in several EOC cell lines when RELA was silenced, indicating its potential tumor suppressive role." (PMID 37175530, 2023). "Evidently, knockdown of NFKB1 and RELA instigated an anti‐tumour effect by suppressing cell proliferation as evidenced by monolayer colony formation assay and by inhibiting cell invasion." (PMID 37983931, 2023). "Nevertheless, constitutive NF-κB p65 (RelA) activation appears to promote the growth and metastasis of tumors by a range of mechanisms, including tumor metastasis, apoptosis, cell proliferation, angiogenesis, and metabolic reprogramming." (PMID 37892820, 2023). "In this regard, therapeutically disabling NF-κB p65 (RelA) expression and enzyme functioning seems like a better approach to disrupting the NF-κB p65 (RelA) inflammatory signaling cascade by preventing the spread and invasion of tumor cells." (PMID 37892820, 2023). "Recent investigations have demonstrated that various tumor cells express NF-κB p65 (RelA) constitutively activated." (PMID 37892820, 2023). "In this study, NF-κB p65 (RelA) and TNFα were found to be highly expressed in many tumor types, including GBM from global databases." (PMID 37892820, 2023). "The vertebrate Rel/NF-kB transcription factors (c-rel, RelA, RelB, NF-kB1 (p50/p105) and NF-kB2 (p52/p100)) play vital roles in immune, inflammatory/stress responses, and are key to tumor survival." (PMID 35742868, 2022). "When comparing the gene expression signature of poorly differentiated (G3) tumours with the moderately differentiated (G2) ones, the downregulation of RELA, NOD1, CASP8, BCL2L1, ELK1, and IKBKB was found." (PMID 36433652, 2022). "Possible mechanisms for ERβ mediated tumor suppression include the formation of co-repressor complexes that suppress the activity of oncogenic NFκB/RELA (p65) and thus inhibit p65 signaling." (PMID 36505861, 2022). "Seven target genes were only knocked down significantly in tumor and RELA was only highly expressed in tumor." (PMID 36329436, 2022). "NGS analysis revealed the synergistic inhibition of NF-κB/RELA target genes and enhanced induction of potential tumor suppressors in response the Gefitinib+IKK16 combination." (PMID 36358633, 2022). "NGS analysis revealed that a subset of the NF-κB/RELA target genes was synergistically suppressed, and expression levels of a series of tumor suppressor genes were elevated by the co-targeting EGFR and IKK with specific small molecule inhibitors." (PMID 36358633, 2022).